PTGES (prostaglandin E synthase)
Diseases named in the same sentence as PTGES in open-access papers (continued):
Sharing a sentence is not in itself a finding about the gene and the disease.
pancreatic adenocarcinoma (1 paper, 2023). "Further, we validated the gene expression regulation by PTGES in another pancreatic adenocarcinoma patient cohort from the GSE57495 study." (PMID 37108468, 2023).
psoriasis (1 paper, 2025). An autoimmune condition characterized by red, well-delineated plaques with silvery scales that are usually on the extensor surfaces and scalp. "Microsomal prostaglandin E synthase-1 (mPGES-1), a terminal enzyme for prostaglandin (PG) E2 biosynthesis, is highly expressed in the skin of psoriasis patients." (PMID 40481552, 2025).
sarcopenia (1 paper, 2023). Progressive decline in muscle mass due to aging which results in decreased functional capacity of muscles. "Despite the fact that the generalizability of the expression level of single genes with a complex functional test seems to be inadequate, the clinical picture presented thus far supports the idea that PTGES and PTGS2 may play a role in the pathology of sarcopenia." (PMID 37629065, 2023).
SARS-CoV infection (1 paper, 2021). "Most were upregulated such as PTGES, MIF, CCR7, CXCL6 and CXCL12, which encodes immune cytokines known to be transcriptionally upregulated during SARS-CoV infection." (PMID 34282405, 2021).
schizophrenia (1 paper, 2016). A major psychotic disorder characterized by abnormalities in the perception or expression of reality. "Regional differences in concentration of cytosolic prostaglandin E synthase (PGES) protein were reported in schizophrenia compared with healthy controls." (PMID 27271499, 2016).
serous ovarian cancer (1 paper, 2022). "On the other hand, the same amplitude of down-regulation of PTGES and PTGDR2 gene expression in the group with serous ovarian cancer grade G3 correlates with relapse-free survival at 6 months and the response to taxanes and platinum treatment, respectively." (PMID 35453789, 2022).
triple-negative breast carcinoma (1 paper, 2023). An invasive breast carcinoma which is negative for expression of estrogen receptor (ER), progesterone receptor (PR), and human epidermal growth factor receptor 2 (HER2). "In addition to hypoxia-mediated regulation of PTGES isoforms, miR-155-mediated upregulation of PTGES has also been reported in triple-negative breast cancer." (PMID 37108468, 2023).
urothelial carcinoma (1 paper, 2020). A malignant neoplasm derived from the transitional epithelium of the urinary tract (urinary bladder, ureter, urethra, or renal pelvis). "Interestingly, some of these genes, such as ETV4, PTGES, CTBP2, FZD6, EAF2, and IKZF6, have not been implicated in urothelial carcinoma; thus, these genes are potential candidates for diagnostic, prognostic, and therapeutic biomarkers of urothelial carcinoma." (PMID 32391279, 2020).
tumor (81 papers, 2006 to 2025). "Interestingly, 5.5% of patients had tumours with amplification of PTGES or PTGES2 or increased expression of the mRNAs they encode." (PMID 31819183, 2020). "Thus, the intrinsic role of PTGES/PGE2 signaling in immunosuppression on tumor cells is linked to its role in induction of the EMT program." (PMID 32060421, 2020). "Besides, butyl isodecyl phthalate and methyl linoleate could be linked to neoplasm by acting on PTGES." (PMID 35702766, 2023). "The expression of PTGS2 and PTGES in orthotopic tumor tissues were notably higher in shNC than in shFADS1 mice, but they were not statistically different in the two groups with the deletion of gut microbes." (PMID 37041160, 2023). "Consistent with sequencing studies, we identified expression of PTGIS and PTGES in both αSMA + fibroblasts and in tumor cells." (PMID 36277993, 2022). "This suggests that, PTGES/PGE2 signaling endows tumor cells resistant to T-cell-mediated cytotoxicity." (PMID 32060421, 2020). "To determine the role of PTGES/PGE2 signaling of tumor cells on T-cell immunity, we performed cytolytical T-cell assay on 1601 and 1601-ko-Ptges cells." (PMID 32060421, 2020). "To extend this analysis further, we further examined, by IHC staining assay, GPRC5A and PTGES in 50 pairs of lung tissues from normal and tumor tissues." (PMID 32060421, 2020). "Mechanistically, PTGES/PGE2 signaling intrinsically endows tumor cells resistant to T-cell cytotoxicity, and induces cytokines extrinsically for MDSC recruitment, which is crucial for suppression of T-cell immunity." (PMID 32060421, 2020). "This suggests that PTGES/PGE2 signaling in the metastatic tumor cells is critical for inhibition of CD8+ T-cell infiltration in lungs." (PMID 32060421, 2020). "To determine the biological impact of PTGES/PGE2 signaling on tumor cells in vivo, we examined the tumorigenicity and lung metastasis of these cells in both immune-deficient nude mice and immune-competent C57BL/6 mice." (PMID 32060421, 2020). "Microsomal prostaglandin E synthase (mPGES) and PGD synthase (PGDS) mediate the final regulatory step of PGE2 and prostaglandin D2 biosynthesis respectively and have been implicated in tumor pathogenesis." (PMID 25886460, 2015). "The prostaglandin E2 (PGE2) synthesis pathway, mediated by cyclooxygenase-2 (COX-2) and microsomal prostaglandin E synthase-1 (mPGES-1), plays a pivotal role in cancer progression by promoting tumor cell proliferation, angiogenesis, immune evasion, and metastasis." (PMID 40564985, 2025). "First, PTGES/PGE2 signaling intrinsically endows tumor cells resistant to T-cell cytotoxicity." (PMID 32060421, 2020). "Taken together, these results suggest that, PGE2 from tumor cells can induce polarization of M2 macrophages in vitro; and PTGES/PGE2 signaling-upregulated TAMs and myeloid cells are strongly correlated with immunosuppression and lung metastasis in Gprc5a-ko mouse lungs." (PMID 32060421, 2020). "Furthermore, siRNA-mediated knockdown of PTGES resulted in a significant reduction in the number of tumor spheres formed from OXR cells." (PMID 30894570, 2019). "Immunohistochemical analyses showed the immunoreactivities of cyclooxygenase-2 and microsomal prostaglandin E synthase-1 in tumor keratinocytes and stronger immunoreactivities of cyclooxygenase-2 and hematopoietic prostaglandin D synthase in epidermal dendritic cells (Langerhans cells)." (PMID 29610553, 2018). "We then analyzed whether the PTGS2 and PTGES are co-expressed/co-induced in cancer cells calculating the Pearson correlation coefficient of their gene expression values for each tumor sample." (PMID 26498686, 2015). "To investigate whether restored PGE2 production and signaling by tumor cells will reverse their resistance to TNF-α–induced killing, we knocked in (KI) the human PTGES gene (hPTGES) into the mouse Ptges-KO D6 clone, denoting these cells as mPtges-KO/hPTGES-KI tumor cells." (PMID 39298269, 2024).
tumor (continued). "In addition, the expression of the enzymes involved in PGE2 synthesis, cyclooxygenase 2 (COX-2) and microsomal prostaglandin E synthase 1 (mPGES1), positively correlates with tumor progression and aggressiveness, clearly indicating the crucial role of the entire pathway in cancer." (PMID 37190301, 2023). "PTGES may further support oncogenesis by suppressing anti-tumor immunity." (PMID 37108468, 2023). "Interestingly, it is tumor cell, and not stromal, expression of PTGES that is associated with a survival advantage in the Maurer data set (Figure A5B)." (PMID 36277993, 2022). "Thus, the therapeutic effects were due to the direct role of PTGES/PGE2 inhibitor on tumor cells." (PMID 32060421, 2020). "By contrast, the over-expressed genes in the networks may trigger tumorigenesis of HNSCC by altering gene expression associated with inflammatory, proliferation, apoptosis and other processes, such as IL6, IGFBP3, ELF3, and PTGES in the both subgroups of tumor cells." (PMID 24069219, 2013). "PTGES is a critical enzyme that catalyzes the conversion of prostaglandin H2 into a prostaglandin E2 (PGE2), which suppresses antitumor immunity and fuels tumor‐promoting inflammation." (PMID 40318167, 2025). "This signature, comprising CCL19, ICOSLG, IL11, PTGES, TNFAIP3, and TRAF3IP3, has been demonstrated to predict survival outcomes across a range of cancers and to correlate with tumor progression at the level of multi‐omics." (PMID 40714831, 2025). "PTGES is one of PGE synthases to catalyze PGE2 synthesis, and it shows inducible expression in immune cells and is up-regulated in inflammation and tumor environment." (PMID 37488601, 2023). "Tumor cells express synthases TBXAS1 (TXA2, TXB2, 12-HHTre) and CYP2S1 (12-HHTre), and some subclusters are enriched for PGE2 synthase PTGES or prostacyclin synthase PTGIS." (PMID 36277993, 2022). "Despite the different numbers of treated and untreated samples analyzed and the diverse levels of gene expression detected in the tumor samples, significantly higher PTGS2 and PTGES was evident in tumors from treated patients." (PMID 32967672, 2020). "However, an increase in the CD8+ T cell population was correlated with lower expression of PTGES, indicating a cytotoxic function of CD8+ T cells in reducing tumor burden." (PMID 37108468, 2023). "These analyses, comparing tumor and normal colon epithelia, showed that gene expressions from several members of this pathway are upregulated in tumors, namely PTGS2, PTGES, and TBXAS1, indicating that the biosynthetic and signaling pathways of PGE2 and TXA2 are favored in established tumors." (PMID 32410997, 2020). "The first tumor-accelerated responses at 1 h after TPA treatment began with genes in “deregulated cellular metabolism”, with the up-regulation of CYP1a1 and CYP1b1, and with genes in “tumor-promoting inflammation”, with the up-regulation of prostaglandin E synthase in prostanoid biosynthesis." (PMID 35328637, 2022).
cancer (56 papers, 2011 to 2025). A tumor composed of atypical neoplastic, often pleomorphic cells that invade other tissues. "In our analysis, PTGES was found to be associated with many important genes belonging to immune pathways implied in cancer and immune cell crosstalk." (PMID 37108468, 2023). "Evaluation of the candidate genes in the eicosanoid biosynthetic pathway identified Ptges (encoding m-PGES1, prostaglandin E synthase), as one of the most significantly downregulated genes in IRE1αKO cancer cells." (PMID 36624093, 2023). "At the transcriptomic level, we found that CCL19 and TRAF3IP3 were protective factors in pan‐cancer, whereas IL11, PTGES, and TNFAIP3 were risk factors." (PMID 40714831, 2025). "PTGES expression is positively correlated with the glycolytic phenotype of cancer cells and can potentially fuel their proliferation and metastasis." (PMID 37108468, 2023). "Makoto Murakami first proposed prostaglandin E synthase as a novel drug target for inflammation and cancer." (PMID 37630311, 2023). "Prostaglandin E2, a product of PTGES, is secreted by cancer cells and binds to G protein-coupled receptors on cancer cells and other cells of the TME." (PMID 37108468, 2023). "Both COX2 and microsomal prostaglandin E synthase 1 (mPGES1) are inducible enzymes typically upregulated in inflammatory situations and both are known to be overexpressed in several cancers." (PMID 33919029, 2021). "Prostaglandin E synthase (Ptges) enriches for numerous mechanisms that endorse cancer growth and progression, such as amplified proliferation, migration and invasion, angiogenesis, counteracted apoptosis, and inflammation." (PMID 32790767, 2020). "Paradoxically, we found a reduced accumulation of arachidonic acid-derived metabolites, including prostaglandin 2, as well as a reduced expression of COX2/PTGS2 and PTGES transcripts in cancer tissue." (PMID 33322148, 2020). "Pharmacological inhibition of microsomal prostaglandin E synthase (mPGES)-1 for selective reduction in prostaglandin E2 (PGE2) biosynthesis is protective in experimental models of cancer and inflammation." (PMID 31231223, 2019). "Similarly, the expression of mPGES-1/PTGES is increased in eight types of cancers but decreased in three types of cancers." (PMID 36765904, 2023). "In conclusion, we propose that PTGES may support oncogenic transformation and metastasis by modulating cancer cell metabolism and hypoxia signaling." (PMID 37108468, 2023). "Therefore, microsomal prostaglandin E synthase (mPGES-1/-2), is a potential target for cancer therapy." (PMID 25871398, 2015). "We further tested whether PTGES could act as an oncogene in other types of cancers." (PMID 37108468, 2023). "Notably, the glycolysis pathway was positively correlated with PTGES and may fuel cancer cell growth." (PMID 37108468, 2023). "PTGES (as PGE2 synthase enzyme) catalyzes endoperoxide PGH2 conversion to PGE2 and it is present and upregulated both in inflammatory tissues and cancer." (PMID 39417702, 2024). "One inflammatory pathway commonly dysregulated in cancer is the metabolism of arachidonic acid (AA) by Cyclooxygenase-2 (COX-2) and microsomal Prostaglandin E Synthase 1 (mPGES-1) into Prostaglandin E2 (PGE2)." (PMID 32655834, 2020). "Thereby, ligand-activation of GPER generates a feedforward loop coupling IL1β induction by CAFs to IL1R1 expression by cancer cells, promoting the up-regulation of IL1β/IL1R1 target genes such as PTGES, COX2, RAGE and ABCG2." (PMID 27072893, 2016). "PTGES induced AKT phosphorylation, resulting in increased HIF‐1α expression, thereby promoting glycolysis in myofibroblasts, which are critical stromal components in cancer cell progression." (PMID 39417702, 2024). "Furthermore, strong correlations of PTGS2 or PTGES and EGR1 mRNA levels in several cancer datasets were found, and particularly in Skrzypczak Colorectal 2 dataset, Pearson's correlation was 0.84 for PTGS2 and EGR1 and 0.647 for PTGES and EGR1 mRNA levels." (PMID 26498686, 2015).
cancer (continued). "We found that SFN indeed blocked PGE2 production in human A549 cancer cells not by inhibiting COX-2, but rather by suppressing the expression of microsomal prostaglandin E synthase (mPGES-1), the enzyme that directly synthesizes PGE2." (PMID 23166763, 2012).
infection (16 papers, 2013 to 2026). The state of being infected such as from the introduction of a foreign agent such as serum, vaccine, antigenic substance or organism. "Prostaglandin E Synthase converts prostaglandin endoperoxide H2 (PGH2) to prostaglandin E2 (PGE2), which is a potent immunoregulatory lipid mediator with key roles in the regulation of virus replication and modulation of inflammatory responses following infection." (PMID 24618842, 2014).
immune system diseases (1 paper, 2018). "DEGs that enriched to “immune system diseases” played critical roles in cell-matrix communication (THY1, LVRN, LUM, TIMP3, SPOCK1, LGALS3BP, FAT2, and SERPINE2) as well as inflammation (IL1R2, CD22, PTGES, TNFSF10, IL2RB, C3, SERPING1, and IL-17RE)." (PMID 30131724, 2018).
psychiatric disorder (1 paper, 2016). A disorder characterized by behavioral and/or psychological abnormalities, often accompanied by physical symptoms. "Since cyclooxygenase-2 (COX-2), microsomal prostaglandin E synthase-1 (mPGES-1), and prostaglandin E2 (PGE2) are involved in neurodegeneration, psychiatric disorders, and pain, these molecules may mediate the pathological effects induced by dsRNA." (PMID 26780827, 2016).
PTGES also shares sentences with these, for which no sentence is quoted: atherosclerosis (8 papers); Arthritis (7); Obesity (6); Alzheimer disease (5); non-small cell lung carcinoma (5); neurodegenerative disease (4); periodontitis (4); renal failure (4); aneurysm (3); cardiac ischemia (3); diabetes (3); ischemia (3); Peritoneal Fibrosis (3); renal fibrosis (3); type 1 diabetes (3); abdominal aortic aneurysm (2); adenocarcinoma (2); autoimmune disease (2); bladder tumor (2); Brain inflammation (2); cardiovascular disease (2); Cerebral ischemia (2); cervical cancer (2); Dysmenorrhea (2); experimental autoimmune encephalomyelitis (2); gastric cancer (2); hepatocellular carcinoma (2); hydronephrosis (2); Hypertension (2); Insulin resistance (2).
A further 89 diseases each share a sentence with PTGES in 2 papers or fewer.